PRDM7 (PR/SET domain 7)
Description:
Histone methyltransferase that selectively methylates 'Lys-4' of dimethylated histone H3 (H3K4me2) to produce trimethylated 'Lys-4' histone H3 (H3K4me3). May play a role in epigenetic regulation of gene expression by defining an active chromatin state.
Synonyms: PFM4; ZNF910
Tractability: PROTAC: ubiquitination databases record sites on it.
Target class: Enzyme; Transferase
Gene: Protein-coding gene on chromosome 16 (90,056,566 to 90,092,072, reverse strand). Ensembl gene ENSG00000126856.
Subcellular location: Nucleus; Chromosome
Subcellular location (Human Protein Atlas): Nuclear speckles
Pathways (Reactome):
Gene expression (Transcription): Generic Transcription Pathway
Gene Ontology:
Molecular function: histone H3K4 methyltransferase activity; protein binding; histone methyltransferase activity
Biological process: chromatin remodeling; regulation of DNA-templated transcription
Cellular component: chromosome; nucleus
Genetic constraint (gnomAD): Loss-of-function variants: 52 observed, 65.4 expected, observed/expected ratio (o/e) 0.8, 90% interval 0.63 to 1. The upper end of that interval is the gene's LOEUF score, 1, which puts it in group 4 of 6, group 1 being the genes least tolerant of losing a copy. Missense variants: 574 observed, 610.72 expected, observed/expected ratio (o/e) 0.94, 90% interval 0.88 to 1.01. Synonymous variants: 192 observed, 218.63 expected, observed/expected ratio (o/e) 0.88, 90% interval 0.78 to 0.99.
Homologues: Orthologues: macaque PRDM9 (84% identical), pig PRDM7 (71% identical), rabbit PRDM7 (67% identical), mouse Prdm9 (60% identical), rat Prdm9 (59% identical), Caenorhabditis elegans set-17 (17% identical). Paralogues in human: PRDM11 (20% identical).
Diseases named in the same sentence as PRDM7 in open-access papers:
PRDM7 is named in the same sentence as 10 diseases in open-access papers, as found by Europe PMC text mining. Sharing a sentence is not in itself a finding about the gene and the disease. The quoted sentences say what the papers report.
breast carcinoma (1 paper, 2015). "Of the two most common HMTs with homozygous deletions, SETDB2 exhibited the highest frequency of homozygous deletion (6.82%) in basal-like samples, and PRDM7 was most frequent (5.79%) in Luminal B breast cancer." (PMID 25537518, 2015). "Two HMT genes, PRDM7 and SETDB2, showed homozygous deletion in more than 2% of breast cancers." (PMID 25537518, 2015). "Although PRDM14 and PRDM7 were also among the HMTs with the highest frequency of amplification or homozygous deletion, respectively, in breast cancer, they were excluded from the qRT-PCR analysis because their expression levels in breast cancer cells were too low for detection (data not shown)." (PMID 25537518, 2015).
lung carcinoma (1 paper, 2019). "On average, the expression levels of PRDM7 were higher in tumor tissues than normal adjacent tissues in all cancer types, but the difference was only statistically significant for lung cancer (p = 1.83e-09)." (PMID 31818313, 2019). "Nevertheless, we observed higher expression of PRDM7 in tumor tissues, especially in lung cancers, suggesting the abnormal expression of PRDM7 could be related to the dysregulation of histone modification in tumor." (PMID 31818313, 2019).
melanoma (1 paper, 2024). A malignant, usually aggressive tumor composed of atypical, neoplastic melanocytes. "Aside from these previously reported potential antigens, we nominated a histone methyltransferases gene (PRDM7) that is restricted in its expression to testis, but is otherwise uniquely expressed in melanoma tumors." (PMID 39515334, 2024).
cancer (4 papers, 2016 to 2024). A tumor composed of atypical neoplastic, often pleomorphic cells that invade other tissues. "The duplication was confirmed in a variety of normal tissues as well as cancer cell lines indicating that this might be a general mechanism to produce an alternative PRDM7 protein without zinc fingers." (PMID 27203728, 2016).
tumor (3 papers, 2019 to 2024). "To further explore the potential consequence of epigenetic mutations, we analyzed DNA methylation and gene expression of gene PRDM7 in data on tumor and normal adjacent tissues from TCGA." (PMID 31818313, 2019).
PRDM7 also shares sentences with these, for which no sentence is quoted: bone marrow failure (1 paper); cardiovascular diseases (1); Fanconi anaemia (1); Huntington disease (1); neurodegenerative disease (1).